SLC39A14 (solute carrier family 39 member 14)
Description:
Electroneutral transporter of the plasma membrane mediating the cellular uptake of the divalent metal cations zinc, manganese and iron that are important for tissue homeostasis, metabolism, development and immunity. Functions as an energy-dependent symporter, transporting through the membranes an electroneutral complex composed of a divalent metal cation and two bicarbonate anions (By similarity). Beside these endogenous cellular substrates, can also import cadmium a non-essential metal which is cytotoxic and carcinogenic (By similarity). Controls the cellular uptake by the intestinal epithelium of systemic zinc, which is in turn required to maintain tight junctions and the intestinal permeability (By similarity). Modifies the activity of zinc-dependent phosphodiesterases, thereby indirectly regulating G protein-coupled receptor signaling pathways important for gluconeogenesis and chondrocyte differentiation (By similarity). Regulates insulin receptor signaling, glucose uptake, glycogen synthesis and gluconeogenesis in hepatocytes through the zinc-dependent intracellular catabolism of insulin. Through zinc cellular uptake also plays a role in the adaptation of cells to endoplasmic reticulum stress (By similarity). Major manganese transporter of the basolateral membrane of intestinal epithelial cells, it plays a central role in manganese systemic homeostasis through intestinal manganese uptake. Also involved in manganese extracellular uptake by cells of the blood-brain barrier. May also play a role in manganese and zinc homeostasis participating in their elimination from the blood through the hepatobiliary excretion (By similarity). Also functions in the extracellular uptake of free iron. May also function intracellularly and mediate the transport from endosomes to cytosol of iron endocytosed by transferrin. Plays a role in innate immunity by regulating the expression of cytokines by activated macrophages.
Synonyms: LZT-Hs4; ZIP-14; KIAA0062; ZIP14; NET34; HCIN; HMNDYT2; cig19
Tractability: Antibody: UniProt places it where antibodies can reach, with high confidence; its Gene Ontology location is reachable by antibodies, with high confidence; UniProt predicts a signal peptide or a membrane-spanning region; the Human Protein Atlas places it where antibodies can reach. PROTAC: UniProt records ubiquitination sites on it; ubiquitination databases record sites on it; its protein half-life has been measured.
Gene: Protein-coding gene on chromosome 8 (22,366,727 to 22,434,129, forward strand). Ensembl gene ENSG00000104635.
Subcellular location: Cell membrane; Apical cell membrane; Basolateral cell membrane; Early endosome membrane; Late endosome membrane; Lysosome membrane
Subcellular location (Human Protein Atlas): Endoplasmic reticulum; Golgi apparatus; Plasma membrane
Pathways (Reactome):
Transport of small molecules: Zinc influx into cells by the SLC39 gene family
Gene Ontology:
Molecular function: manganese ion transmembrane transporter activity; monoatomic cation:bicarbonate symporter activity; zinc ion transmembrane transporter activity; cadmium ion transmembrane transporter activity; iron ion transmembrane transporter activity; monoatomic anion:monoatomic cation symporter activity; ferrous iron transmembrane transporter activity; metal ion transmembrane transporter activity
Biological process: import across plasma membrane; intracellular zinc ion homeostasis; iron import into cell; iron ion transmembrane transport; manganese ion transmembrane transport; zinc ion import across plasma membrane; zinc ion transmembrane transport; cellular response to glucose stimulus; cellular response to insulin stimulus; chondrocyte differentiation; gluconeogenesis; insulin receptor signaling pathway; intracellular monoatomic cation homeostasis; manganese ion homeostasis; positive regulation of G protein-coupled receptor signaling pathway; regulation of hormone levels; transmembrane transport; bicarbonate transport; cadmium ion transmembrane transport; metal ion transport; monoatomic anion transmembrane transport
Cellular component: apical plasma membrane; basolateral plasma membrane; early endosome membrane; late endosome membrane; lysosomal membrane; membrane; plasma membrane
Genetic constraint (gnomAD): Loss-of-function variants: 19 observed, 47.06 expected, observed/expected ratio (o/e) 0.4, 90% interval 0.28 to 0.59. The upper end of that interval is the gene's LOEUF score, 0.59, which puts it in group 2 of 6, group 1 being the genes least tolerant of losing a copy. Missense variants: 447 observed, 647.79 expected, observed/expected ratio (o/e) 0.69, 90% interval 0.64 to 0.75. Synonymous variants: 263 observed, 261.77 expected, observed/expected ratio (o/e) 1, 90% interval 0.91 to 1.11.
Homologues: Orthologues: chimpanzee SLC39A14 (99% identical), macaque SLC39A14 (94% identical), rabbit SLC39A14 (87% identical), mouse Slc39a14 (86% identical), rat Slc39a14 (86% identical), pig SLC39A14 (85% identical), dog SLC39A14 (83% identical), guinea pig SLC39A14 (82% identical), tropical clawed frog slc39a14 (66% identical), zebrafish slc39a14 (63% identical). Paralogues in human: SLC39A8 (45% identical), SLC39A10 (32% identical), SLC39A6 (31% identical), SLC39A4 (28% identical), SLC39A12 (28% identical), SLC39A5 (24% identical).
Diseases named in the same sentence as SLC39A14 in open-access papers:
SLC39A14 is named in the same sentence as 108 diseases in open-access papers, as found by Europe PMC text mining. Sharing a sentence is not in itself a finding about the gene and the disease. The quoted sentences say what the papers report.
Parkinsonism (25 papers, 2016 to 2026). Characteristic neurologic anomaly resulting from degeneration of dopamine-generating cells in the substantia nigra, a region of the midbrain, characterized clinically by shaking, rigidity, slowness of movement and difficulty with walking and gait. "While pathogenic variants in SLC39A14 (Mn transporter) were classically associated with dystonia-parkinsonism phenotypes, a recent update by the MDS Task Force for the Nomenclature of Genetic Movement Disorders classified this condition as DYT-SLC39A14." (PMID 40362326, 2025). "In 2016, bi-allelic mutations in SLC39A14 were identified in individuals with features of Mn neurotoxicity, such as rapidly progressing dystonia, variable parkinsonism, and T1 hyperintensity in the globus pallidus observed on brain MRI." (PMID 40278159, 2025). "This systematic review explores the genotype–phenotype correlations of GLB1, SLC6A3, SLC30A10, PLA2G6, and SLC39A14—recently classified as DYT SLC39A14 and historically linked to dystonia-parkinsonism." (PMID 40362326, 2025). "Mutations in SLC39A14 result in swiftly advancing dystonia accompanied by varying degrees of parkinsonism and other neurological symptoms, typically beginning in infancy or early childhood." (PMID 40278159, 2025). "Second, we found no apparent accumulation of Mn—which has been shown to cause parkinsonism symptoms—in the brain in Slc39a11 knockout animals for Slc30a10 and Slc39a14 knockout animals." (PMID 39114488, 2024). "Homozygous mutations of this family of transporters (SLC30A10, SCL39A8, SLC39A14) cause a rare pediatric genetic disease characterized by hypermagnesemia, parkinsonism and dystonia, liver disease and polycythemia, and specific imaging signs." (PMID 37627255, 2023). "In humans, loss of function mutations in SLC39A14 are responsible for childhood-onset dystonia parkinsonism, with SLC30A14 deficiency producing hypermanganesemia and neurodegeneration." (PMID 35745255, 2022). "Currently, the etiological factor in the SLC39A14 mutation-induced dystonia-parkinsonism is presumed to be the highly toxic concentrations of Mn measured in the blood and brain." (PMID 36361624, 2022). "Over the last decade, several clinical reports have outlined cases of childhood-onset manganese (Mn)-induced dystonia-parkinsonism, resulting from loss-of-function mutations in the Mn influx transporter gene SLC39A14." (PMID 36361624, 2022). "Since 2016, an increasing number of clinical reports have described a progressive childhood-onset dystonia-parkinsonism resulting from inherited, autosomal recessive, loss-of-function mutations of the SLC39A14 gene." (PMID 36361624, 2022). "First described by Tuschl and colleagues in 2016, inherited loss-of-function mutations of the SLC39A14 gene results in an early onset, progressive dystonia-parkinsonism." (PMID 36361624, 2022). "SLC39A14 is a divalent metal transporter known to be associated with neurodegeneration and early-onset Parkinsonism-dystonia." (PMID 34542594, 2021). "Mutations in SLC39A14 lead to rapidly progressive dystonia with variable parkinsonism and other neurological signs with onset during infancy or early childhood." (PMID 31089831, 2019). "Recently, however, mutations in the SLC39A14 gene have been linked to manganese (Mn) accumulation in the brain and childhood-onset parkinsonism dystonia." (PMID 28751976, 2017). "The patients with a homozygous mutation in SLC39A14 have increased levels of Mn in the blood and brain at an early age and develop dystonia-parkinsonism." (PMID 28751976, 2017). "In this study, we have identified a novel autosomal recessive disorder of Mn homeostasis caused by homozygous mutations in SLC39A14 that lead to early-onset rapidly-progressive parkinsonism–dystonia and neurodegeneration." (PMID 27231142, 2016).
Parkinsonism (continued). "In this review article, we will describe the current understanding and ongoing studies on the pathophysiology of Childhood-Onset Dystonia-Parkinsonism in SLC39A14 mutation carriers and new knowledge gained from the availability of experimental animal models with global deletion of the Slc39a14 gene." (PMID 36361624, 2022). "In 2016, bi-allelic mutations in SLC39A14 were identified in individuals who presented with typical features of Mn neurotoxicity including rapidly progressive dystonia with variable signs of parkinsonism and T1-hyperintensity of the globus pallidus on brain MRI [26••]." (PMID 31089831, 2019). "Moreover, mutations in the human SLC39A14 gene have been suggested to affect Mn transport primarily in hepatocytes, thereby underlying the parkinsonism dystonia seen in patients with such mutations; data obtained with a transgenic zebrafish model appear to support this notion." (PMID 28751976, 2017). "Mutations in SLC39A14 can induce parkinsonism dystonia-like (PD-like) symptoms as a result of Mn accumulation in various brain structures, particularly the globus pallidus and striatum." (PMID 28751976, 2017). "This review on GLB1, SLC6A3, SLC30A10, SLC39A14, and PLA2G6 is the third MDSGene review series on DYT/PARK genes, following previous articles on DRD genes and X-linked dystonia-parkinsonism." (PMID 40362326, 2025). "The original publication on SLC39A14 reported patients with concurrent dystonia and parkinsonism, initially leading to its classification as a progressive parkinsonism-dystonia syndrome." (PMID 40362326, 2025). "Clinical cases of parkinsonism have been described in relation to the homozygous mutations in the solute carrier (SLC) transporters, which mediate the influx (SLC39A8, SLC39A14) and efflux (SLC30A10) of Mn." (PMID 37627255, 2023). "Dysfunction of SLC39A14 would impair hepatic manganese uptake, and promote rapidly progressive childhood-onset parkinsonism-dystonia." (PMID 36906575, 2023). "In summary, the recent advances in understanding the role of SLC39A14 function in modulating Mn homeostasis and neurotoxicity has provided novel information of Mn-induced dystonia-parkinsonism." (PMID 36361624, 2022). "Brain Mn accumulation with parkinsonism is also observed in patients harboring loss-of-function mutations in the Mn efflux transporter SLC30A10 (also known as ZNT10) and the uptake transporter SLC39A14 (also known as ZIP14)." (PMID 37482277, 2023). "Given the predominantly neurological presentation of these conditions, it is likely that missing data on cardinal signs/symptoms, such as parkinsonism in GLB1, SLC30A10, and SLC39A14, reflect their actual absence." (PMID 40362326, 2025). "Impaired hepatic and enterocytic manganese uptake (SLC39A14) and excretion (SLC30A10) lead to deposition of manganese in the basal ganglia resulting in childhood-onset dystonia-parkinsonism." (PMID 40320765, 2025). "With the exception of SLC6A3 and PLA2G6, which primarily manifest with dystonia and parkinsonism as key features, we found that GLB1, SLC30A10, and SLC39A14 predominantly exhibit a dystonic phenotype, sometimes accompanied by other movement disorders, such as parkinsonism or ataxia." (PMID 40362326, 2025). "Similarly, loss-of-function mutations in SLC39A14 have been reported in patients with high blood levels of Mn and accumulation of Mn in the brain (but not in the liver) and with juvenile-onset dystonia-parkinsonism, and Slc39a14-deficient mice again model these human phenotypes." (PMID 39435657, 2024). "However, we observed that the proportion of individuals manifesting parkinsonism in GLB1, SLC30A10, and SLC39A14 is lower than expected under the DYT/PARK nomenclature, where dystonia and parkinsonism should generally coexist or be prominent features in approximately half or more of the patients." (PMID 40362326, 2025).
Dystonia (24 papers, 2016 to 2025). An abnormally increased muscular tone that causes fixed abnormal postures. "The identification of patients with mutations in SLC39A14 that result in Mn overload and early‐onset dystonia highlights SLC39A14's crucial role in Mn transport." (PMID 41177175, 2025). "Rare genetic variants in SLC30A10 or SLC39A14 have been linked to hypermanganesemia with dystonia and neurotoxicity." (PMID 41178719, 2025). "In this study we present two infants presenting with dystonia and hypermanganesemia caused by a homozygous missense variant in SLC39A14, a recently recognized gene involved in Mn homeostasis in humans, thus expanding the very few descriptions of this disorder." (PMID 29382362, 2018). "A customized gene panel for movement disorders revealed a novel missense variant (c.311G > T; p.Ser104Ile) in SLC39A14 gene in two siblings presenting at the age of 10 months with acute dystonia and motor regression." (PMID 29382362, 2018). "Karin Tuschl, Philippa Mills and colleagues report mutations in the manganese (Mn) transporter gene SLC39A14 in childhood-onset parkinsonism-dystonia." (PMID 27231142, 2016). "Similarly, mutations in SLC39A14, another Mn transporter, have been associated with childhood-onset Parkinsonism-dystonia and hypermanganesemia." (PMID 41497916, 2025). "By six months of age, Slc39a14−/− mice began to show signs of dystonia with a progressive inability to coordinate their motor activity; these symptoms are similar to the PD-like motor disability in patients with a mutation in SLC39A14." (PMID 28751976, 2017).
liver fibrosis (11 papers, 2020 to 2025). "Knockout of SLC39A14 expression in Trf-LKO mice effectively decreases hepatic iron accumulation, consequently reducing ferritin deposition-associated hepatic fibrosis induced by a high-iron diet or CCl4 injection." (PMID 37978473, 2023). "Decreased SLC39A14 expression in liver significantly reduces iron accumulation, thereby reducing liver fibrosis mediated by ferroptosis." (PMID 36313616, 2022). "As expected, the conditional knockout of hepatic SLC39A14 reduces iron accumulation in liver and ferroptosis-mediated liver fibrosis, indicating that SLC39A14-mediated iron uptake promotes ferroptotic liver injury and disease." (PMID 33117818, 2020). "In the presence of iron overload, Slc39a14 transports iron and mediates the development of ferroptosis, thereby affecting the development of various diseases, such as glucolipid metabolism disorders, liver fibrosis and intestinal dysfunction." (PMID 37301835, 2023). "Conversely, upregulation of SLC39A14 in hepatocyte-specific TFR knockout mice leads to ferroptosis due to excess iron, making them more prone to liver fibrosis." (PMID 39396974, 2024). "SLC39A14 transferred non-transferrin-bound iron into the mouse liver resulting in ferroptosis to promote liver fibrosis." (PMID 38602575, 2024).
hepatocellular carcinoma (9 papers, 2018 to 2025). A malignant tumor that arises from hepatocytes. "Another recent study demonstrated that the expression level of SLC39A14 is amplified in hepatocellular carcinoma cells and tissues." (PMID 32729666, 2020). "Immunohistochemical analysis showed the expression level of SLC39A14 was significantly higher in hepatocellular carcinoma tissues than that in adjacent tissues and negatively correlated with survival time." (PMID 31565549, 2019). "ZIP14/SLC39A14 is a metal transporter regulating uptake of zinc and it is downregulated in hepatocellular cancer and prostate cancer, and alternatively spliced in colorectal cancer." (PMID 36299481, 2022).
prostate carcinoma (9 papers, 2017 to 2025). A carcinoma that arises from epithelial cells of the prostate gland. "Accordingly, the decreased expression of SLC39A14 was associated with aggressiveness and the relapse of prostate cancer, and alternative splicing of SLC39A14 was associated with colorectal cancer." (PMID 35625809, 2022). "SLC39A14 has been identified as an independent factor for predicting the biochemical recurrence-free survival of patients with prostate cancer, and the decreased expression of SLC39A14 is associated with the tumor aggressiveness of human prostate cancer." (PMID 30446011, 2018). "Low expression of SLC39A14 in prostate cancer promotes tumor cell proliferation, invasion and migration." (PMID 37978473, 2023). "However, in prostate cancer patients, reduced expression of SLC39A14, which serves as a tumor suppressor, may lead to malignant phenotypes and aggressive tumor progression." (PMID 38602575, 2024).
Cachexia (8 papers, 2019 to 2023). Severe weight loss, wasting of muscle, loss of appetite, and general debility related to a chronic disease. "The study has shown that the overexpression of SLC39A14 in skeletal muscle contributes to the development of cachexia in metastatic malignancies." (PMID 37978473, 2023).
Sepsis (8 papers, 2014 to 2023). Sepsis is defined as life-threatening organ dysfunction caused by a dysregulated host response to infection. "In other diseases, SLC39A14 upregulation activates NO, a key regulator of the cGMP-PKG pathway, mediating hepatic zinc accumulation and hypozincemia during inflammation and sepsis." (PMID 37978473, 2023).
renal cell carcinoma (7 papers, 2020 to 2025). "circ_000829 acts as an anticancer agent in renal cell carcinoma via inhibiting SRSF1-mediated selective splicing of SLC39A14." (PMID 38581057, 2024). "In renal cell carcinoma (RCC), miR-502-5p impaired the proliferation and metastasis of RCC cells via decreasing SLC39A14 expression." (PMID 33758619, 2021). "SLC39A14 through Circ_000829 and SRSF1-mediated alternative splicing suppression, plays an anticancer role in renal cell carcinoma." (PMID 37978473, 2023). "In renal cell carcinoma (RCC), opposing roles are seen for zinc transporters; ZIP1 is a downregulated tumor suppressor that reprograms metabolism to restrain growth, whereas SLC39A14 is upregulated via a circRNA-miRNA axis to promote tumorigenesis." (PMID 41583444, 2025). "In renal cell carcinoma (RCC) tissues, like in NPC, the mRNA expression of SLC39A14 was significantly enhanced; inhibiting SLC39A14 might impair the migration, invasion, proliferation, and epithelial-mesenchymal transition (EMT) of RCC cells." (PMID 38602575, 2024).
breast carcinoma (6 papers, 2016 to 2021). "Our findings were consistent with those of the previous study, in that high mRNA expression levels of SLC39A6 and SLC39A14 indicated favorable OS, but upregulated SLC39A2-5, SLC39A7, and SLC39A12-13 were associated with poor OS in the patients with breast carcinoma." (PMID 34925450, 2021).